EGFR (epidermal growth factor receptor)
Diseases named in the same sentence as EGFR in open-access papers (continued):
Sharing a sentence is not in itself a finding about the gene and the disease.
breast carcinoma (continued). "Neither secoiridoids nor lignans treatments caused detectable changes in HER1 (EGFR) expression in breast cancer cells (data not shown)." (PMID 19094209, 2008). "In addition to ERBB2, EGFR is overexpressed in basal-like breast cancer and is a possible target for new anti-breast cancer reagents." (PMID 19007432, 2008). "Epidermal growth factor receptor (EGFR) is involved in regulating cell growth in breast carcinomas." (PMID 18522728, 2008). "Moreover, a higher proportion of the evaluated CTCs was stained positive for EGFR in patients with metastatic than in patients with early breast cancer." (PMID 18822183, 2008). "Numerous studies have shown that EGFR/HER2-elicited signaling is involved in human breast cancer." (PMID 18518979, 2008). "This could probably be explained by the observation that human breast cancer is often characterized by a gradual progression to an estrogen-independent, EGFR-positive, and highly metastatic phenotype." (PMID 18822183, 2008). "Regarding EGFR, a recently published study reported that EGFR protein expression, assessed by IHC, was a negative prognostic marker in the absence of paclitaxel in patients with high-risk operable breast cancer." (PMID 18985033, 2008). "The objective of this study was to investigate whether EGFR and phosphorylated EGFR are expressed on CTCs isolated from the blood of patients with breast cancer." (PMID 18822183, 2008). "EGFR is generally considered to be a negative prognostic factor in breast cancer, but up to now, no definitive association between EGFR expression and survival has been demonstrated." (PMID 18985033, 2008). "We examined a range of breast cancer cell lines with varying levels of EGFR and TNK2." (PMID 18435854, 2008). "It has been estimated that 45% of human breast carcinomas overexpress EGFR (range, 14–91%)." (PMID 18985033, 2008). "Moreover, EGFR expression had also been shown to play a role in hormone resistant breast cancer patients and this has led to the use of Iressa with aromatase inhibitors in breast cancer." (PMID 18682844, 2008). "In fact, it has recently been reported that nuclear localization of EGFR is detected in the highly proliferating state of human cancer tissues in vivo and human breast cancer cell lines in vitro, supporting the close correlation between nuclear EGFR and tumor tissues with high proliferation." (PMID 18492291, 2008). "We questioned whether RSK1 or RSK2 may play a role in BLBC because they lie in the MAP kinase pathway, which is commonly activated in this type of breast cancer due to overexpression of EGFR." (PMID 19036157, 2008). "Although the small number of patients examined precludes firm conclusions, this finding further suggests that EGFR signaling may be involved in breast cancer progression." (PMID 18822183, 2008). "In some cases, co-targeting EGFR and YB-1 may be necessary to optimally inhibit the growth of these aggressive breast cancer cells." (PMID 17875215, 2007). "In at least one small trial, there was evidence of only minimal efficacy in advanced, metastatic ER- breast cancer, though one could make the conjecture that anti-EGFR therapy might be more effective in less advanced cancers." (PMID 17598908, 2007). "Moreover, the ER-, HER2-, CK5/6+ and/or EGFR+ profile seems to correlate better with basal-like breast cancer gene expression profiles." (PMID 17650314, 2007). "There is increasing knowledge on the pivotal role of epidermal growth factor receptor (EGFR) together with HER2 in breast carcinoma and how it may influence downstream signal transduction pathways that regulate cell survival and proliferation." (PMID 17662123, 2007).
breast carcinoma (continued). "Our observations imply that targeting this interaction or the use of a 'ligand trap' like sFRP1 might be a valid approach to treat breast cancer by interfering with the canonical WNT pathway as well as the EGFR/ERK1/2 pathway." (PMID 17897439, 2007). "HER3 is frequently overexpressed in breast cancers with EGFR or HER2 overexpression." (PMID 17667926, 2007). "Our results, showing that Wnt1 transactivates EGFR in tumor cell lines, imply that, in breast cancer, constitutive WNT signaling might impact not only on the canonical pathway, but also on EGFR activity by stimulating ligand availability." (PMID 17897439, 2007). "This may have implications for the effectiveness of anti-EGFR therapies in breast cancer as HRGβ1 is enriched in many EGFR-positive breast tumours." (PMID 17686159, 2007). "Previous studies from our group have established that growth of a tamoxifen-resistant MCF-7 (Tam-R) breast cancer cell line is driven by the autocrine release of the epidermal growth factor-like ligand amphiregulin and activation of the EGFR/MAPK signalling pathway." (PMID 17686159, 2007). "Similarly, an inhibitor of EGFR was shown to inhibit Stat3 activation and it was shown that high EGFR was positively correlated with Stat3 in breast cancer." (PMID 17531096, 2007). "The basal cytokeratin-negative tumors that clustered with the basal-like cluster in this study could be EGFR, vimentin, and/or c-kit-expressing tumors with a similar gene expression signature to that of basal cytokeratin-immunopositive breast cancers." (PMID 17263897, 2007). "In breast cancer patients, the response rate to single agent EGFR inhibitors has been low, however, these trials were performed on unselected patient populations and response rates might be improved within biologically selected tumor subsets." (PMID 17663798, 2007). "In the present study we have examined whether HRG signalling can circumvent EGFR blockade in an EGFR-positive tamoxifen-resistant MCF-7 (Tam-R) breast cancer cell line." (PMID 17686159, 2007). "We concluded that irrespective of 'activating mutations' in EGFR, Iressa inhibits the growth of basal-like breast cancer cells." (PMID 17875215, 2007). "Breast cancer is a heterogeneous disease arising from at least two distinct epithelial cell populations, therefore, we selected cell lines models of basal-like and luminal cells to begin our investigations of the EGFR-pathway." (PMID 17663798, 2007). "Epidermal growth factor receptor inhibitors are effective in blocking HER2 mediated signalling in HER2 overexpressing breast cancer cell lines that co-express the EGFR, and combinations of EGFR and HER2 targeted agents have been shown to have additive or synergistic effects on growth inhibition." (PMID 16622439, 2006). "EGFR and its ligand, transforming growth factor-alpha (TGF-alpha) play an important role in several human cancers, through the autocrine growth-regulation system in breast cancer, EGFR has been reported to be associated with a poor clinical outcome." (PMID 17092354, 2006). "Although we acknowledge the potential applicability of CISH in ascertaining HER2 gene amplification in breast cancer patients who are candidates for trastuzumab therapy, the scoring system proposed for EGFR FISH in NSCLC currently cannot be extrapolated to CISH technology." (PMID 16911776, 2006). "A clinically relevant issue is the identification of potential predictive factors, which could help to select breast cancer patients who could respond to anti-EGFR targeted therapies." (PMID 16685276, 2006). "The combination of increased LRIG1 copy number and protein expression and low EGFR/ERBB1 expression might represent a subtype of breast cancer with its own clinical features." (PMID 16168117, 2005). "Because most metaplastic breast carcinomas overexpress EGFR without gene amplification, further studies to evaluate EGFR activating mutations are warranted." (PMID 16280056, 2005).
breast carcinoma (continued). "In addition, when EGFR is overexpressed in carcinomas with heterologous elements and matrix producing breast carcinomas, its expression appears to be more conspicuous in epithelial components (data not shown)." (PMID 16280056, 2005). "Interestingly, EGFR and HER2 coexpression in breast cancer was recently associated with reduced overall survival (OS) and disease-free survival (DFS)." (PMID 16280056, 2005). "Interestingly, a recent study on anti-EGFR antibody treatment of breast cancer cells showed a decrease in the cell-replication rate with a corresponding reduction in hnRNP K expression levels." (PMID 16033304, 2005). "In order to improve the antineoplastic activity of gefitinib, we investigated the effects of blocking the signalling of the insulin-like growth factor 1 receptor (IGF-1R), a tyrosine kinase with a crucial role in malignancy that is coexpressed with EGFR in most human primary breast carcinomas." (PMID 15987464, 2005). "However, Weber and coworkers recently described EGFR missense mutations in sporadic and familial (BRCA1/BRCA2 related) breast cancer and demonstrated that these mutations are significantly more frequent in the latter." (PMID 16280056, 2005). "This suggests an effect of progestins similar to that observed in breast cancer cell lines, although it is unclear whether high EGFR levels correlate with higher proliferation or with tissue differentiation." (PMID 15987425, 2005). "Finally, estrogen-dependent breast cancer cells synthesize and secrete growth factors in response to E2 which can stimulate the epidermal growth factor receptor signaling pathway to induce proliferation." (PMID 15642158, 2005). "We investigated whether HER2 and EGFR overexpression was present and evaluated gene amplification in a series of metaplastic breast carcinomas." (PMID 16280056, 2005). "Our findings suggest that some patients with metaplastic breast carcinomas might benefit from novel therapies targeting EGFR." (PMID 16280056, 2005). "Moreover, EGFR over-expression and Her2 amplification are both correlated with ER negativity in human breast cancers in vivo." (PMID 16457695, 2005). "In addition, a series of experimental and clinical findings have suggested that aberrant activation of tyrosine receptor kinases, such as EGFR/HER1 and HER2 pathways, play a causal role in the development of antioestrogen resistance in breast cancer." (PMID 14710235, 2004). "Immunostaining for EGFR was positive in 32% (10/31) of samples comprising of 1 breast carcinomas, 5 colon carcinomas, 1 ovarian carcinoma, 1 sarcoma, 1 skin melanoma and 1 carcinoma of unknown primary site." (PMID 15560844, 2004). "It has been reported that EGFR/HER1 is expressed at high levels in at least 20% of breast cancers." (PMID 14710235, 2004). "However, inhibiting both EGFR/HER2 and MAPK signalling can result in significant growth inhibition and apoptosis of EGFR-expressing breast cancer cells." (PMID 15280923, 2004). "The EGFR pathway may also play an important role in oestrogen-independent breast cancer, and one group has presented preclinical data suggesting that hormone independent cells are more sensitive to EGFR TKIs than wild-type cells." (PMID 15150574, 2004). "In the present study, we generated protein-based PLC-γ1 inhibitors consisting of PLC-γ1-SH2 domains fused to the TAT leader sequence as highly specific inhibitors to block PLC-γ1 tyrosine phosphorylation, thereby inhibiting the EGF-induced migration of EGFR/c-erbB-2-positive breast cancer cells." (PMID 14710234, 2004). "The goals of the present study were to characterise the pattern of expression of activated ERK1/2 in established breast cancer cell lines and determine whether this correlates with EGFR or HER2 status." (PMID 15280923, 2004). "The relationship between EGFR/c-erbB-2 heterodimer signalling and gelsolin activation in breast cancer cells has been called the ‘master switch’ hypothesis." (PMID 14710234, 2004).
breast carcinoma (continued). "Using the breast carcinoma cell line MDA-MB 468 as immunogen, we have produced six new rat monoclonal antibodies (mAbs) against the human EGF receptor (EGFR) and are investigating their use for diagnostic and therapeutic applications in cancer patients whose tumours overexpress these receptors." (PMID 8094290, 1993). "In conclusion, EGFR status appears to be a significant and independent indicator of recurrence in human breast cancer and the concomitant measurement of the tumour proliferative activity seems to improve the selection of patients with different risks of recurrence." (PMID 1419645, 1992). "Yet, given the efficacy of the nontargeted approach, it could be used to treat locally advanced breast cancers of various phenotypes (not limited to EGFR‐positive), questioning the value of the targeted system, as nontargeted probes are easier to implement in clinics." (PMID 40395357, 2025). "Consequently, breast cancer cells may activate compensatory signaling pathways, thereby reducing the efficacy of anti-EGFR therapies." (PMID 41516015, 2025). "In addition, integrins and focal adhesion proteins modulate treatment resistance in a variety of tumour cells, including glioma, breast cancer and uroepithelial carcinoma, through interactions with growth factor (GF) receptors such as epidermal growth factor receptor (EGFR)." (PMID 40045379, 2025). "One explanation for the limited success of EGFR TKIs in breast cancer is that following EGFR inhibition, other receptors and/or cell surface proteins activate and/or heterodimerize, which provides alternative growth and survival signaling cascades downstream of EGFR, such as the MEK/MAPK pathway." (PMID 40560045, 2025). "By targeting cytoskeletal integrity and EGFR signaling, it may disrupt cytokine and tumor–microenvironment interactions, supporting further exploration as a strategy to overcome resistance in lung and breast cancers." (PMID 41401147, 2025). "Moreover, flow cytometry using breast cancer cell lines with varied expression levels of EGFR indicated that BP-αCD3-αEGFR-ARC Exos along with CD9-CD38/αCD3-αEGFR Exos and αCD3-αEGFR Exos can tightly bind to EGFR-positive BT-20 and MDA-MB-231 cells, but not EGFR-negative MDA-MB-453 cells." (PMID 41419470, 2025). "Similarly, some gene alterations with matched therapies occurred at relatively higher frequencies in on-label cancer types, including alterations in PIK3CA (42.2% in on-label HR+/HER2- breast cancer vs. 10.6% in off-label cancers) and in EGFR (19.8% in on-label NSCLC vs. 0.1% in off-label cancers)." (PMID 40711866, 2025). "Further, this study characterized a model looking at TNBC, however ER+HER2− patients had a statistically significantly worse OS, therefore there are likely other breast cancer patient populations with EGFR amplification and PI3K alteration who might benefit from this dual therapy." (PMID 40501689, 2025). "Additionally, it was able to inhibit the EGFR signalling pathway in human breast cancer cell lines." (PMID 40427522, 2025). "Therefore, we suggest that AREG acts as an intermediary between EGFR and ER and targeting both ERs and EGFRs through combination therapy could prevent tumor progression in EGFR+ ER+ breast cancer patients." (PMID 40422206, 2025). "Hence, TCDD may inhibit growth factor-driven EGFR signal transduction in early stages of breast cancer, whereas it is probably ineffective in doing so in advanced stages, when TCDD-activated AHR may dominate and drive tumor progression." (PMID 39996234, 2025).
breast carcinoma (continued). "Similar results were observed in MCF7/PalbR and T47D/PalbR cells upon exposure to the EGFR inhibitor gefitinib (data not shown), in accordance with previous studies indicating that EGFR inhibition may blunt the proliferation of palbociclib resistant breast cancer cells." (PMID 38886784, 2024). "Additionally, EGFR is overexpressed in around 14% of breast carcinomas." (PMID 39482666, 2024). "Based on these previous results, we hypothesized that EGFR expression levels could affect the treatment of HER2+ breast cancer patients through dimerization with HER2+, further leading to differences in reactivity to anti-HER2 antibodies such as trastuzumab (TRZ) and trastuzumab emtansine (T-DM1)." (PMID 39791720, 2024). "The variation in results compared to previous studies may be due to small sample size, differences in tissue processing, the type of assay used for EGFR measurement, the cut-off values for EGFR positivity, variation in breast cancer subtypes or ethnic disparities." (PMID 39405290, 2024). "Additionally, our prognostic analysis of genes encoding proteins in the EGFR/PI3K/AKT signalling pathway and GPX4 in breast cancer revealed that reduced activation of the EGFR/PI3K/AKT pathway and decreased GPX4 expression were associated with better patient outcomes." (PMID 39881871, 2024). "However, the use of small molecule EGFR tyrosine kinase inhibitors (TKIs) alone has shown minimal clinical effectiveness though with reduced side effects as compared with conventional chemotherapeutic drugs in breast cancer patients." (PMID 38522013, 2024). "In addition, NT5DC2 mediates the malignant growth of breast cancer by blocking the EGFR pathway." (PMID 39506204, 2024). "However, it is unclear whether the interaction of breast cancer cells with endothelial cells influences EGFR activation, and which downstream signalling molecules are involved." (PMID 38762624, 2024). "Another future direction could include investigation of the role of macropinocytosis in cholesterol uptake: how common it is in breast cancer and weather it is involved in the cholesterol uptake in ovarian cancer as well, what can regulate it in addition to EGFR and Ras?" (PMID 39243069, 2024). "As an oral dual HER2/EGFR tyrosine kinase inhibitor, lapatinib could provide anti-cancer efficacy in pretreated and trastuzumab-resistant breast cancer patients, and the combination of trastuzumab and lapatinib improved the outcome in the neoadjuvant and metastatic setting." (PMID 38611014, 2024). "Similarly, cetuximab, another targeted therapeutic agent that binds to the extracellular domain of EGFR and inhibits the activation of downstream signaling pathways, has demonstrated efficacy in the treatment of breast cancer by inducing apoptosis in tumor cells." (PMID 39796003, 2024). "In accordance with our findings, previous studies have suggested that inhibiting EGFR palmitoylation with 2-BP could decrease EGFR PM localization, reduce EGFR protein expression, and sensitize lung and breast cancer cells to EGFR-targeted tyrosine kinase inhibitors (TKIs) treatments." (PMID 38263401, 2024). "In conclusion, the inhibition of EGFR‐mediated tumorigenesis of aggressive breast CSCs by the compound 1e in combination with a low dose of doxorubicin will effectively reduce the tumor growth in TNBCs that provide a therapeutic way forward to reduce the relapse of breast cancer." (PMID 38522013, 2024). "Macrophage-induced expression of EGFR may lead to tamoxifen resistance in breast cancer." (PMID 38339428, 2024). "Thus, suggesting EGFR as a molecular therapeutic target against breast cancer tumorigenesis." (PMID 38522013, 2024). "More than ten years later, Feng and colleagues discovered that breast cancer cells could escape lapatinib (an oral dual tyrosine kinase inhibitor that targets epidermal growth factor receptor-EGFR and HER2) and consequently survive by displaying a change toward CD36-mediated FA uptake 61,69." (PMID 38370376, 2024).